MIR520D (microRNA 520d)
Synonyms: hsa-mir-520d; MIRN520D
Gene: MicroRNA gene on chromosome 19 (53,720,096 to 53,720,182, forward strand). Ensembl gene ENSG00000207735.
Gene Ontology:
Biological process: miRNA-mediated post-transcriptional gene silencing